CD44 (CD44 molecule (IN blood group))
Diseases named in the same sentence as CD44 in open-access papers (continued):
Sharing a sentence is not in itself a finding about the gene and the disease.
lymphopenia (17 papers, 2010 to 2023). Reduction in the number of lymphocytes. "The exception was normal numbers of mature CD8+ T cells in the LckCA/CA and LckCA/KR mice, apparently due to lymphopenia-induced proliferation coupled with the generation of CD44+ antigen-inexperienced memory-like CD8+ T cells in these mice." (PMID 36564464, 2023). "Memory‐like populations can be generated during lymphopenia and include CD44+ virtual memory cells that accumulate with age." (PMID 31832191, 2019). "This is also in line with observations from lymphopenia-derived memory T cells, which upregulated CD44 and elicited effector functions, including rapid IFN-γ secretion." (PMID 31024566, 2019). "The hyperexpansion of CD8+ T cells driven by lymphopenia may transiently display effector functions prior to differentiation of memory-like T cells, which is coupled to the presence of CD44, CD122 (interleukin 2 receptor β), and Ly6C to secret IFN-γ." (PMID 31649684, 2019). "However, the lymphopenia-induced activation is evident from the increase in the expression of CD44 and decreased expression of CD62L even at 4 weeks of age." (PMID 27023180, 2016). "Lymphopenia-associated IL-7 overabundance contributes to the activation of naïve T cells, which undergo homeostatic or lymphopenia-induced proliferation (LIP) and convert into memory-like cells, which express high levels of CD44 and IFNγ." (PMID 27447484, 2016). "Since Themis–/– mice have a higher proportion of CD44hi cells due to lymphopenia, we gated on CD44lo cells for our analysis of CD5, CD6 and CD44 expression." (PMID 33897691, 2021). "In thiswork, we investigated the relationship between the expression of the surfacemarkers CD44 and CD62L and the functional properties of CD8+ T cellsunder lymphopenia." (PMID 33959391, 2021). "Phenotypic analysis of the T cells showed increased frequency of CD44+ and significantly higher expression of Tbet and IFNγ in PTPN22 KO CD4 T cells after they underwent lymphopenia induced proliferation." (PMID 32047502, 2020). "At 12 months of age, there was a distinct population of CD8+CD62L+CD44+ cells in the CKO mice, which represent “memory phenotype” cells that have undergone homeostatic proliferation in response to lymphopenia." (PMID 30022979, 2018). "Despite severe decreases in splenic T cell numbers, there was no upregulation of CD44 or downregulation of CD62L in spleen, changes that characterize T cells that have undergone lymphopenia-induced homeostatic proliferation." (PMID 20405040, 2010). "Similarly, data from a mouse model in which another essential autophagy gene, Atg5, was deleted under the hematopoietic stem cell-specific promoter Vav, showed T cell lymphopenia and the expanded virtual memory T cell compartment (CD8+CD44+) suggesting this phenotype is not Atg7 specific." (PMID 25385531, 2014).
Hepatic steatosis (16 papers, 2013 to 2025). Steatosis is a term used to denote lipid accumulation within hepatocytes. "A number of recent studies have described a critical role for CD44–HA interactions in the pathogenesis of fatty-liver disease, the leading cause of chronic liver disease in United States and a growing problem worldwide." (PMID 25741341, 2015). "Increased CD44 at both the RNA and protein levels has been found to be associated with hepatocyte ballooning and alanine aminotransferase levels in patients with hepatic steatosis, metabolic dysfunction-associated steatohepatitis (MASH), or hepatitis B virus (HBV) infection." (PMID 38731968, 2024). "Consequently, mice deficient in CD44 show a reduced hepatic steatosis, reduced inflammatory infiltrate in white adipose tissue and improved glucose tolerance." (PMID 30949049, 2019). "We next examined whether CD44-deficiency had any affect on the development of HFD-induced hepatic steatosis." (PMID 23505504, 2013). "To obtain further insights into the function of CD44 in metabolic syndrome, we compared the development of diet-induced hepatic steatosis, WAT-associated inflammation, and type 2 diabetes between wild type (WT) mice and mice deficient in CD44 expression (CD44KO)." (PMID 23505504, 2013). "To obtain further insights into the potential role of CD44 in metabolic syndrome, we monitored the development of diet-induced hepatic steatosis, adipose-associated inflammation, and type 2 diabetes in WT and CD44KO mice fed with a HFD ((WT(HFD) and CD44KO(HFD), respectively) for 21 weeks." (PMID 23505504, 2013). "Previous study has reported increased CD44 expression in the liver of obese mice, with CD44 deletion shown to reduce liver steatosis." (PMID 41002415, 2025). "The altered expression of these genes collectively attenuated liver steatosis in HFD-treated CD44-KO mice." (PMID 38731968, 2024). "CD44 deficiency in the B6 background inhibited the development of hepatic steatosis; CD44.B6 mice had a 56.7% reduction in hepatic TG content compared to B6 males." (PMID 35410390, 2022). "CD44 expression augments in liver and white adipose tissue in obese patients as well as rodents and correlates with liver steatosis and type 2 diabetes." (PMID 30949049, 2019). "In that study, Cd44−/− mice were also protected from hepatic steatosis, displayed significantly smaller livers when compared to wild-type counterparts, and had significantly reduced serum liver enzyme values." (PMID 23762326, 2013). "Recent studies showed a correlation between the level of CD44 expression and hepatic steatosis in obese patients." (PMID 23505504, 2013). "Our study support and extend recent findings demonstrating the role of CCR2 and CD44 in inflammation during hepatic steatosis." (PMID 23762326, 2013). "Our data reveal the independent and overlapping roles of CCR2 and CD44 in development and progression of hepatic inflammation during fatty liver disease." (PMID 23762326, 2013). "CD44 expression in obese patients was significantly elevated compared with lean healthy individuals, and its expression was significantly correlated with the grade of hepatic steatosis." (PMID 38731968, 2024). "Measures of hepatic steatosis and insulin sensitivity were improved in CD44-deficient mice on a C57BL/6J but not in the C3H/HeJ mice." (PMID 35410390, 2022). "We observed a significant upregulation of TIPRL, LC3, and CD44 in tissues of hepatocyte-derived liver diseases such as chronic hepatitis, hepatic steatosis, liver cell degeneration, liver tissue degeneration, and inflammation of the porta area, compared with normal tissues." (PMID 34208132, 2021). "Therefore, one might hypothesize that the reduced hepatic steatosis and WAT-associated inflammation in CD44KO mice might be due in part to the inability of Opn to activate the CD44 pathway." (PMID 23505504, 2013).
liver fibrosis (16 papers, 2012 to 2025). "Based on the association of CD44 with liver fibrosis, targeting CD44 is emerging as a potential therapeutic strategy for orchestrating liver fibrosis." (PMID 38790021, 2024). "Inhibition of Snail1 causes the downregulation of Nanog and CD44 and loss of self-renewal, as evidenced by decreased liver fibrosis formation." (PMID 23226767, 2012). "Experimental models of lung, skin, heart, and liver fibrosis demonstrate that genetic deletion of CD44, its pharmacological blockade, or inhibition of HA biosynthesis leads to inhibition of the progression of fibrogenic changes." (PMID 41009438, 2025). "Proteomic analysis of serum from patients with FALD also recently demonstrated that soluble CD44 concentrations in serum and liver correlated with liver fibrosis severity." (PMID 40738518, 2025). "CD44 expression was also found in the liver following pIVCL, and blockade of CD44 was found to attenuate liver fibrosis." (PMID 40738518, 2025). "CD44 upregulation has been reported in liver diseases such as metabolic dysfunction-associated steatotic liver disease (MASLD), liver fibrosis, and hepatitis C virus (HCV) infection." (PMID 38731968, 2024). "The current study also showed alleviation of HSC activation and liver fibrosis by TSG-6 interacting with CD44 in ALD mice." (PMID 38790021, 2024). "Based on these findings, CD44 seems to contribute to liver fibrosis through a β-catenin-related pathway regulating S100A4 expression in congestive hepatopathy." (PMID 38731968, 2024). "During the progression of liver fibrosis, enhanced expression of CD44 in HSCs was accompanied by an elevation of S100A4, promoting HSC activation and fibrosis." (PMID 38731968, 2024). "In the ALD mouse model, MMP14 at both the RNA and protein levels was upregulated with increased CD44 activity and liver fibrosis." (PMID 38790021, 2024). "ERK2−/− hepatic lymphocytes display less the percentages of CD44 expression in the comparison to WT upon liver fibrosis." (PMID 32471201, 2020). "Hence, further research is required to unveil the molecular mechanisms that explain how CD44-mediated cell transitions induce liver fibrosis." (PMID 38731968, 2024). "However, it is not yet known how CD44 expression in BECs increases, or how BECs with upregulated CD44 promote liver fibrosis in damaged livers." (PMID 38731968, 2024). "Given that TSG-6 bound with CD44 to inactivate HSCs, we examined whether TSG-6 influenced CD44 activation to reduce liver fibrosis in EtOH-fed mice." (PMID 38790021, 2024). "However, TSG-6 treatment notably downregulated MMP14 at both the RNA and protein levels, similar to the effect of decreasing CD44 activity and liver fibrosis in the EtOH-treated mice." (PMID 38790021, 2024). "Wijaya demonstrated that KLRG1+ NK cells relied on the bone-bridging proteins TRAIL and CD44 to promote HSC apoptosis and mitigate hepatic fibrosis." (PMID 40244063, 2025). "Previously, our group showed that the interaction of TSG-6 with CD44 activated β-catenin/YAP-1 signaling and reprogrammed activated HSCs into stem-like cells, mitigating HSC activation and liver fibrosis in mice with chronic liver damage from CCl4." (PMID 38790021, 2024). "The synthesized peptide YJ successfully mimics TSG-6 action, preventing CD44 cleavage by obstructing MMP14 activity in HSCs and alleviating hepatic fibrosis." (PMID 38790021, 2024). "TSG-6 interacted directly with the catalytic site of MMP14, a proteolytic enzyme that cleaves CD44, inhibited CD44 cleavage to CD44ICD, and reduced HSC activation and liver fibrosis in ALD mice." (PMID 38790021, 2024). "In various animal models of liver fibrosis, such as the MASH model and carbon tetrachloride (CCl4)-induced or bile duct ligation-induced liver fibrosis model, higher levels of CD44 have been reported." (PMID 38731968, 2024). "HSCs express CD44 and TLR4, and HSC activation upregulates the expression of CD44 in liver fibrosis." (PMID 36930869, 2023).
liver fibrosis (continued). "TSG-6 binding to CD44 masked the proteolytic cleavage region of CD44 from matrix metalloproteinase 14 (MMP14), blocked CD44ICD generation in HSCs, and suppressed HSC activation and liver fibrosis in ALD mice." (PMID 38790021, 2024). "CD44 cleavage to CD44ICD leads to HSC activation and liver fibrosis." (PMID 38790021, 2024). "Hence, it is possible that TSG-6 physically inhibits the catalytic activity of MMP14 and protects CD44 cleavage to CD44ICD from MMP14 to reduce HSC activation and liver fibrosis in mice with ALD." (PMID 38790021, 2024). "Contrarily, in cirrhosis, the end stage of liver fibrosis, TIPRL, LC3, and CD44 were downregulated." (PMID 34208132, 2021). "Our group has previously reported that the absence of OPN reversed HFD-induced fatty liver, suggesting that OPN and its corresponding receptor CD44 play a critical role in liver fibrosis, as both are decreased in the absence of the iNOS gene." (PMID 30818874, 2019). "ECM components are responsible for increased matrix stiffness in liver fibrosis and may influence expression of c-SRC via growth factor or hyaluronan receptors (e.g., CD44) or focal adhesion complexes." (PMID 26696895, 2015). "Comparable pathological changes were observed in livers isolated from Cd44+/+;Nf2flox/flox;Alb-Cre, Cd44−/−;Nf2flox/flox;Alb-Cre, and Cd44flox/flox;Nf2flox/flox;Alb-Cre mice, suggesting that the status of the Cd44 gene has no influence on ductular proliferation or liver fibrosis." (PMID 37174657, 2023).
bladder tumor (15 papers, 2014 to 2024). "The aim of the study was to identify if aggressive bladder tumor growth mediated by AGL loss depends on either CD44 or RHAMM or both." (PMID 27595989, 2016). "Increased CD44 expression has been associated with a better outcome in cancers such as bladder tumors and could potentially relate to cell-cell interaction as a marker for potential invasion/metastasis." (PMID 24491153, 2014). "Intensive yellow staining provided evidence for a prominent co-expression of tumor marker GATA-3 and the AE1/AE3 reactive cytokeratins on UCO#33 by immunofluorescence as well as co-expression of bladder tumor-associated antigens CD24 and of CD44." (PMID 37626918, 2023). "Research has shown that CD47 is expressed in all human bladder tumors, most notably in CD44+ cells." (PMID 36937442, 2023). "Overall glycoproteogenomics analysis of different cell models and bladder tumors supported transcriptomics data and provided a mass spectrometry-based approach for validation of several CD44 exon-exon junctions, moving one step forward in the characterization of this glycoprotein." (PMID 35547758, 2022). "Moreover, colocalization of CD44 with Oct4 was detectable, albeit in a small percentage of cells, in human bladder tumor xenografts that were resistant to cisplatin treatment." (PMID 27244887, 2017). "However, several studies have shown that CD44 expression is associated with a better outcome in cancers such as bladder tumors and other studies have suggested no direct association of CD44 with prognosis in cancers such as skin tumors." (PMID 24491153, 2014). "TFCP2L1‐positive cells in bladder tumors displayed high expression levels of SALL4 and CD44 CSC markers." (PMID 31709755, 2020). "In one such experiment, the CD44 splice isomer (CD44v6) was used to separate the CD44v6+ epithelial membrane antigen negative (EMA-) stem cell subtype from bladder tumors." (PMID 29029546, 2017). "We sorted BCSCs and non-BCSCs from bladder tumor tissues through flow cytometry with CD44." (PMID 26143634, 2015).
invasive ductal carcinoma (15 papers, 2011 to 2025). "Next, we assessed the expression of SH3RF3 and CD44 at the protein level in a Qilu cohort of 40 breast invasive ductal carcinomas by immunofluorescence (IF) staining." (PMID 32427938, 2020). "We studied the correlation between epidermal growth factor receptor (EGFR) and the tumor stem cell markers CD44/CD24 in breast invasive ductal carcinoma (BIDC) and their relationship with prognosis." (PMID 25429827, 2015). "In an immunohistochemistry breast invasive ductal carcinoma study Oliveira-Costa and collaborators demonstrated the relation between CD44 expression and HIF1-Alpha status and HER-2 expression influencing the patient prognosis." (PMID 23419168, 2013). "Increased expression of CD44s, the most common isoform of CD44, has been observed in invasive ductal carcinoma, but has been found to have a positive effect on patient survival." (PMID 22937154, 2012). "We therefore determined the percentage of CD44+/CD24- cells in tissue samples from 147 invasive ductal carcinomas." (PMID 22762532, 2012). "The prevalence of CD44+/CD24- tumor cells varied greatly in invasive ductal carcinomas, with the occurrence of this phenotype high in primary tumors with high PR status and in secondary tumors." (PMID 22762532, 2012). "A total of 147 randomly selected primary and secondary invasive ductal carcinoma samples were assayed for expression of CD44, CD24, ER, PR, and Her2." (PMID 22762532, 2012). "CD44 co-localised extensively with Flotillin-1 in the cell membranes of ductal carcinoma in situ cultures, but there was little spatial overlap of these proteins in invasive ductal carcinoma cultures." (PMID 24512624, 2014). "Research on the correlation between EGFR expression and CD44/CD24 and their prognostic value in breast invasive ductal carcinoma (BIDC) is limited." (PMID 25429827, 2015). "The presence of CD44 and CD24 antigens on invasive ductal carcinoma tissues was analyzed using double-staining immunohistochemistry." (PMID 22762532, 2012). "CD44+/CD24- phenotype: This phenotype may be an important factor for malignant relapse after surgery and chemotherapy in invasive ductal carcinoma." (PMID 40236653, 2025). "Accordingly, lower levels of palmitoylated CD44 were detected in whole cell extracts from six representative invasive ductal carcinoma cultures relative to two representative nontumour cultures." (PMID 24512624, 2014). "Moreover, the presence of CD44+/CD24-/low tumor cells was associated with a shorter cumulative DFS and OS, suggesting that the CD44+/CD24- phenotype may be an important factor of malignant relapse in patients with surgically resected invasive ductal carcinoma after chemotherapy." (PMID 22762532, 2012). "CD44 is closely related to tumor resistance, and the CD44+/CD24− phenotype may be an important factor of malignant relapse with chemoresistance in patients with surgically resected invasive ductal carcinoma." (PMID 30849956, 2019). "Thus, the CD44+/CD24- phenotype may be an important factor for malignant relapse following surgical resection and chemotherapy in patients with invasive ductal carcinoma." (PMID 22762532, 2012).
Pleural effusion (15 papers, 2008 to 2023). The presence of an excessive amount of fluid in the pleural cavity. "Compared with PD-1 inhibitor group, the number of cancer cells, ki-67 proliferation index and CD44 expression in the pleural effusion was significantly decreased and the lymphocyte/cancer cell ratio was significantly increased in the chimeras/AuNP-CM group." (PMID 36082168, 2022). "In MM patients, a high concentration of HA in the pleural effusion fluid or serum and an overexpression of CD44 were reported." (PMID 30061637, 2018). "Limited by the low cell numbers of some samples, the expression of CD44+CD24-/low was evaluated in 13 out of 18 (72%) pleural effusions." (PMID 28423035, 2017). "The isolated cells were sorted within a median time of 8 days after collection of pleural effusion aspirates for cancer stem cell markers CD44+/CD24-/low and ALDH1+." (PMID 28423035, 2017). "Expression of CD24 and CD44 on uncultured cells and mammospheres derived from the pleural effusions was documented." (PMID 18541018, 2008). "With this background, we examined cells in samples of pleural effusions for the presence of a CD44+/CD24low/- subpopulation and for their ability to grow in non-adhesive conditions as mammospheres." (PMID 18541018, 2008). "Using the same CD24 antibody used by Al Hajj and colleagues (ML5) and the same CD44 antibody, we found that only some pleural effusion samples yielded subfractions of cells and these could be detected whether or not the cells were first gated as ESA+ (data not shown)." (PMID 18541018, 2008). "Recent work has characterized the cellular heterogeneity of human breast tissues based on cell surface expression of CD44 and CD24, using epithelial cells from primary reduction mammoplasty tissues, pleural effusions, and primary tumors." (PMID 18366788, 2008). "One of the stored pleural effusions, PE14, which formed large mammospheres (average 100 μm) that were highly tumorigenic, showed an unusual phenotype in that all of the cells in the uncultured population were negative for surface expression of CD24 and CD44." (PMID 18541018, 2008).